E2F3 (E2F transcription factor 3)
Diseases named in the same sentence as E2F3 in open-access papers (continued):
Sharing a sentence is not in itself a finding about the gene and the disease.
cancer (151 papers, 2005 to 2026). A tumor composed of atypical neoplastic, often pleomorphic cells that invade other tissues. "E2F3 is the only E2F member that is linked to cancer and is a potent and direct regulator of Igf2, with its role in adipose tissue still not clear." (PMID 41361331, 2025). "The E2F3 is an oncogene that has been implicated in various cancers and is associated with poor prognosis." (PMID 39129166, 2025). "The E2F3 TF drives the cell cycle from G1 to S phase, and alterations in E2F3 function are also associated with poor prognosis in various cancers." (PMID 39045407, 2024). "E2F transcription factor-3 (E2F3) plays an oncogenic role in tumourigenesis, and changes in its function are associated with a poor prognosis in different types of cancers, highlighting its significance in clinical cancer outcomes." (PMID 38132457, 2023). "Among others, E2f1, E2f3, Kif13a, Rxra, Rxrb, and Rxrg were the most common and prominent genes that emerged in our analysis associated with multiple cancer-related pathways." (PMID 37047531, 2023). "E2F3, located on chromosome 6p22, has been shown to be significantly upregulated in cancers and is associated with malignancy progression, including proliferation and cell cycle process." (PMID 35237319, 2022). "Cg14751398 was the largest hub node in the UCEC network, located on E2F3, which is linked to poor prognosis in some cancers as an oncogenic factor." (PMID 36676027, 2022). "Transcription factor E2f3 plays an important role in regulating the cell cycle, and its dysregulation has been implicated in human cancers." (PMID 34173119, 2021). "As we expected, tumors formed in the presence of E2F3-deficient cancer cells, displaying reduced weight and volume along with significantly less HIF-2α expression." (PMID 28903320, 2017). "E-Cadherin, Vimentin, ZEB1, and N-Cadherin were introduced as the indicators in cancer progression, and their fluctuations were associated with the E2F3 and HIF-2α change." (PMID 28903320, 2017). "These genes control the characters of invasion, migration and proliferation and thus BMI-1 have been implicated as proto-oncogenes and E2F3 the transcriptional factor attractive therapeutic targets against cancer." (PMID 25367080, 2014). "We investigated the Src, Ras, β-catenin and E2F3 pathways, which have previously been shown to be associated with survival in other types of cancer." (PMID 23950933, 2013). "Similarly, the enforced expression of miR-34a (transfection of pre-miR-34a) was observed to target anti-apoptotic protein Bcl-2, c-Myc, Cyclin D1, E2F3 and Notch signaling pathway, causing the suppression of cancer cell proliferation, metastasis and invasion." (PMID 38139352, 2023). "A caveat of this finding is that other cancer-associated genes, such as E2F3, are located adjacent to ID4 at Chr6q22 and so may also be a target of the amplification event." (PMID 32527287, 2020). "This upregulation of miR-141-3p and/or miR-200a-3p may have effects on several cancer-related target genes that have been previously associated with these two miRNAs, including E2F3, GLS, CCND2, PTEN, CCNG1, CDC25B, and ZFPM2." (PMID 28288173, 2017). "Therefore, E2F3 might be a newly identified diagnostic and potential therapeutic target for solid human cancers." (PMID 30967995, 2019). "Thus, the ability of PPIX to inhibit cancer cell may be associated with E2F3 suppression by miR-199a-5p." (PMID 25714015, 2015). "E2F3 is a key regulator of cell cycle progression and has established oncogenic roles in multiple cancers." (PMID 41372977, 2025). "Meanwhile, numerous target genes of miR-34c-5p have been identified in cancers, such as E2F3, BCL-2, and c-Met." (PMID 37670265, 2023). "E2F3 upregulation has been detected in several human cancer types which reportedly drives cell proliferation, differentiation, cell cycle progression, and apoptosis resistance." (PMID 37647439, 2023).
cancer (continued). "Meanwhile, we found E2F3 (transcription factor 3), which correlated with poor prognosis in a variety of cancers, was negatively regulated HOOK1 transcription though directly binding to the HOOK1 promoter by VHL dependent manner in RCC." (PMID 37085921, 2023). "More importantly, previous study has proven that E2F1/E2F3/Caspase-3 axis is an effective mechanism in cancer suppression which not only can advance apoptosis level in cancer cell but also inhibit stemness, invasion, migration, etc.." (PMID 36175803, 2022). "Both E2F1 and E2F3, as oncogenes, are involved in the regulation of many biological properties, such as cancer stemness and apoptosis." (PMID 36175803, 2022). "Mechanistically, E2F3-induced MEX3A overexpression sustains cancer cells in a rapidly dividing and undifferentiated state by directly suppressing KLF4, a key pro-differentiation regulator, to activate WNT signaling." (PMID 36276637, 2022). "recently showed that cell cycle signaling was associated with high cancer stemness of EAC, such as E2F3, CHEK1, CDC20, SMC3, and TFDP1." (PMID 35785171, 2022). "We similarly found a significant enrichment in E2F‐4 and E2F‐3 transcription factors with the enrichment analysis of differentially expressed genes in carcinoma." (PMID 35488454, 2022). "DEK encodes a DNA-binding protein that is a known oncogene in multiple other cancers, while E2F3 is crucial for transcriptional cell cycle control and is regulated by the RB protein pRB." (PMID 34283049, 2021). "In NSCLC, E2F3 improves the malignancy of cancer cells by increasing the expressions of cyclinD1, cyclinD2, and CDK4 while inhibiting p21 and p57 expressions." (PMID 34346845, 2021). "Among 12 genes reported in the literature as SL with RB1 6 genes (PPWD1, SKP2, AURKA, AURKB, E2F1, and E2F3) scored as SL RB1 partners in human cancer patients." (PMID 33591981, 2021). "E2F3 expression correlates with prognosis in a variety of cancers, highlighting the importance of E2F3 in determining the clinical cancer phenotype." (PMID 33618745, 2021). "miR-210 can attenuate cancer cell activity through downregulating E2F3, fibroblast growth factor receptor-like 1, homeobox protein Hox-A1, homeobox protein Hox-A9 and Max-binding protein." (PMID 33673181, 2021). "Keigo Araki and colleagues show that E2F3d, a previously unidentified isoform of transcription factor E2F3, mediates hypoxia-induced mitophagy in cancer cells." (PMID 30740539, 2019). "Aberrant activity and expression of the E2F3 transcription factor is frequently observed in many cancer cells." (PMID 30740539, 2019). "E2F3a is particularly important for promoting cell proliferation, and E2F3 gene amplification and overexpression of E2F3 are detected in several types of human cancers, especially high-grade cancers." (PMID 30740539, 2019). "Here we show that E2F3d, a previously unidentified E2F3 isoform, mediates hypoxia-induced mitophagy in cancer cells." (PMID 30740539, 2019). "In transwell and wound-healing assays, knocking down E2F3 abolished the ability of HOXB9 in enhancing cancer cell migration." (PMID 29724991, 2018). "An increasing amount of evidence suggested that E2F3 can trigger cancer cell growth and proliferation." (PMID 28903320, 2017). "We explored the influence of E2F3 transcriptional activity on the HIF-2α expression in cancer cells by using real-time techniques." (PMID 28903320, 2017). "Recently, increasing evidences have confirmed that miR-210 functions as an oncogene in many types of cancers by degrading its targets such as E2F3, Casp8ap2 and ATM." (PMID 28415557, 2017). "Among the 112 cancer specimens, elevated E2F3 immunostaining was observed in 48.2% (54 of 112) cytoplasm and 55.3% (62 of 112) nuclei." (PMID 28903320, 2017).
cancer (continued). "In cardiovascular diseases and cancers, E2F3 was also testified as a representative target of miR-125b and miR-195." (PMID 28947999, 2017). "Alterations in E2F3 functions correspond with poor prognosis in various cancers, underscoring their status for the clinical cancer phenotype." (PMID 28947999, 2017). "The multiple relationships between miRNA or E2F3 and human cancers, as well as the finding that E2F3 is coordinated by miRNAs have attracted more attention from numerous researchers." (PMID 28947999, 2017). "We focused on the role of E2F3 and HIF-2α in ccRCC carcinogenesis in vitro, as well as on the subcellular localization of E2F3 in cancer tissues and its clinical significance." (PMID 28903320, 2017). "For instance, miR-429 mediated suppression of EMT has also been correlated with miR-429 directly targets Onecut2, BMI-1 and E2F3, MiR-429 enhances cancer cell apoptosis under chemotherapy by targeting Bcl-2 and AP-2α." (PMID 27058893, 2016). "Given the role of E2F3 in the promotion of cancer cell proliferation, we next determined the effect of PPIX on DNA synthesis using [3H]-thymidine incorporation assay." (PMID 25714015, 2015). "Taken together, these observations point to the importance of E2F3 as a key player in cancer progression." (PMID 25889255, 2015). "It is important to note that E2F3 and AKT3 are both the predicted targets of miR-15, whose deletion was proved to be associated with cancer." (PMID 25821802, 2015). "Knockdown of E2F3 (siE2F3) also suppressed the rate of DNA synthesis (right), suggesting that E2F3 attribute at least in part to cancer cell proliferation." (PMID 25714015, 2015). "In SK-TRb cells, T3 down-regulated mRNA levels of Ccnd2, Cdk6, Cdc25, E2f3, c-Myb, Wee1 and Chk1 involved in cell proliferation and cancer." (PMID 24796297, 2014). "A similar reduction was found in the ‘HG_U133A’ data set (10 normal mucosa samples and 80 cancers) with the average RB1/E2F3 ratio dropping −0.63-fold (log 2 scale) from normal mucosa to cancer (P=0.019, Student's t-test)." (PMID 19156145, 2009). "A comparison of the RB1/E2F3 transcript ratios revealed a significant reduction of −1.97 fold (log 2 scale) from normal mucosa to cancer (P=8.96 × 10−8, Student's t-test)." (PMID 19156145, 2009). "E2F3 IHC analysis of a commercial TMA containing normal mucosa as well as benign and malignant colorectal specimens revealed that E2F3 was significantly higher expressed also at the protein level in the majority of cancers compared with normal mucosa." (PMID 19156145, 2009). "Median E2F3 mRNA expression was 2.24 arbitrary units in cancers compared to 0.72 in normal tissues, i.e. about threefold higher." (PMID 15876350, 2005). "Furthermore, overexpression of the oncogene E2F transcription factor 3 (E2F3) promotes the development of different cancers and is related to the HPV E6 and E7 oncogenes." (PMID 38342922, 2024). "In addition, miR-34a-5p has been found to modulate cancer cell proliferation and invasion through regulating E2F3 and surviving expression." (PMID 38819446, 2024). "Furthermore, E2F3-overexpressing cancer cell lines display increased IGF2 expression, which can provide an LOI-independent mechanism for IGF2 regulation in cancer." (PMID 37371750, 2023). "The transcription factor E2F3 (E2F transcription factor 3) is oncogenic in cancer." (PMID 37240338, 2023). "E2F3 has been confirmed to be an oncogene in a variety of cancers." (PMID 37456248, 2023). "The specific relevance of E2F3 to immune activity in cancers has been proposed as well." (PMID 37647439, 2023). "Compared to the benign tissue, PCa tissue showed an up-regulated expression of E2F3 (benign vs cancer = 1.49 ± 0.05 vs. 1.86 ± 0.02, p < 0.01), and a higher expression of E2F3 was also related to higher Gleason scores (GS < 7: 1.62 ± 0.06, GS = 4 + 3: 1.73 ± 0.04, GS > 7: 2.04 ± 0.04)." (PMID 35531101, 2022).
cancer (continued). "Under the same conditions, the Caspase-3 activity has been improved by VA, which indicates that E2F1/E2F3/Caspase-3 axis may be one of the anti-cancer mechanism of VA." (PMID 36175803, 2022). "Several studies have demonstrated that E2F3 is a cancer-promoting gene in EC." (PMID 35676262, 2022). "Overexpression of E2F3 is frequently observed in various cancers." (PMID 33854603, 2021). "Although E2F3 mediates cancer cell proliferation, angiogenesis, antiapoptotic activity, invasion and metastasis, the functions and underlying mechanisms of E2F3 in ccRCC are still unknown." (PMID 33618745, 2021). "Previous studies indicated that miRNAs regulate the expression of E2f3 in various types of cancers." (PMID 34173119, 2021). "E2F3, a potent transcriptional inducer of cell-cycle progression, was dysregulated in many cancers." (PMID 34873170, 2021). "E2F3, a member of E2F family, was widely revealed to promote cancer initiation and progression." (PMID 32228703, 2020). "The overexpression or amplification of E2F3 was common in various cancers, and its reduction could deter cancer progression." (PMID 33232580, 2020). "We speculate that miRNA‐126‐3p may target E2F2 and E2F3 to restrain the cell proliferation and cancer progression of LUSC." (PMID 32598517, 2020). "Interestingly, the two hub genes, E2F2 and E2F3, were all involved in these cancer‐related pathways." (PMID 32598517, 2020). "Recently, the clear oncogenic role of E2F3 was revealed in several human cancers." (PMID 30967995, 2019). "And we found that one TF, E2F3 was related to ESCA, two genes, DTNA and KCNMA1 were related to STAD, while one TF ESR1 and one gene KIT were associated with both of the two types of cancer." (PMID 31888440, 2019). "Interestingly, bioinformatics analysis of TCGA cancer database showed that HOXB9 expression is positively correlated with E2F3 expression." (PMID 29724991, 2018). "E2F3 was reported overexpressed in multiple tumors, and correlated with cancer metastasis." (PMID 29724991, 2018). "Considering the cancer type-depending dysregulation of miRNAs/E2F3 loops, this deregulation may play an intricate role in carcinogenesis." (PMID 28947999, 2017). "Identification of the reciprocal link between E2F3 and miRNAs may help to extended our understanding of carcinogenesis and develop potential therapeutic strategies against cancer." (PMID 28947999, 2017). "Recently, studies revealed the involvement of E2F3 in cancer progression." (PMID 28903320, 2017). "Interestingly, HIF-2α overexpression was able to rescue the inhibition of cancer cell proliferation by E2F3 knockdown." (PMID 28903320, 2017). "Further studies are needed to identify whether disrupting the E2F3-HIF-2α interaction could be a promising way of combating cancer progression and metastasis of ccRCC tissues." (PMID 28903320, 2017). "Current understanding of the reciprocal link between E2F3 and miRNAs in human cancers were summarized, which could help to develop potential therapeutic strategies." (PMID 28947999, 2017). "To ascertain whether HIF-2α could be regulated by E2F3, we inhibited and overexpressed E2F3 in different cancer cell lines." (PMID 28903320, 2017). "In summary, our data elucidated that cytoplasmic E2F3 was upregulated in high stage cancer." (PMID 28903320, 2017). "E2F3 is overexpressed in various cancers and drives tumorigenesis." (PMID 27285756, 2016). "To assess whether E2F3 levels were higher in an aggressive type of cancer, we comparatively evaluated the protein levels in a set of epithelial and mesenchymal liver tumor cells." (PMID 25714015, 2015).
cancer (continued). "Other miRNAs such as miR-20a, -34a, -125b, -200b, -217, and -503 may also suppress E2F3 and induce cancer cell apoptosis." (PMID 25714015, 2015). "E2F-1 levels, as well as E2F-3 levels have been shown to be increased in several human cancers." (PMID 24658650, 2014). "Since E2F3 interacts with the retinoblastoma tumor suppressor protein (pRb), we also investigated pRb expression and detected a severe downregulation, to actual inactivation of pRb protein in the same cancer samples." (PMID 20421977, 2010). "Previous studies have also reported that SOX-2 and E2F3 may promote the migration of cancer cells." (PMID 38864530, 2024). "Interestingly, when MYCN is high, the simple downregulation of RB1 is ineffective on cell growth or on reduction of cancer aggressiveness as implied by the Kaplan Meier graphs in which it is shown that E2F3 and MYCN expressions are strong prognostic markers of clinical outcome independently of RB1." (PMID 36982482, 2023). "Current studies indicate that E2F2 and E2F3 may act as vital regulators in several cancers." (PMID 32598517, 2020). "Additionally, it has been verified that the inhibition of E2F3 induced by overexpression of miRNAs could enhance the sensitivity of HCC patients to anti-cancer agents and decelerate the progression of HCC." (PMID 29298665, 2018). "By comparing the lists of top-ranking cancer-related target genes, we were able to identify seven promising cancer-related genes that may be targets of the hsa_circRNA_100395/miR-141-3p/ miR-200a-3p axis in PTC (in order of descending rank): E2F3, GLS, CCND2, PTEN, CCNG1, CDC25B, and ZFPM2." (PMID 28288173, 2017). "Thus, HIF-1α and E2F3 may share common roles in the progression of cancers through the miRNAs identified." (PMID 25714015, 2015). "While the downregulated DEGs in the Control vs. Poly I: C treated group of Gaddi dogs showed pathways highlighting, such as in cancer with NOTCH2, MDM2, and E2F3, the pathway related to RNA metabolism was also enriched for genes such as HNRNPA3 and XPO1." (PMID 40621499, 2025). "In ESC, E2F3 overexpression induces RACGAP1 expression, thereby enhancing the cancer-promoting effect of RACGAP1." (PMID 37504265, 2023). "For such reasons, inclusion of E2F3 in expression screening panels to identify and properly treat IGF2-driven cancers in adults has a proper rationale." (PMID 37371750, 2023). "On the other hand, E2F3 and CD24, which are also commonly dysregulated in cancer were classified as NAP genes in our analysis as they were up-regulated in at least 30% of the patients but were not identified by the all-patients analysis." (PMID 36737737, 2023). "E2F3 belongs to the E2F transcription factor family; E2F1 and E2F3 are involved in maintenance and self-renewal of cancer stem cells." (PMID 35444695, 2022). "The miR-141-3p was found to be down-regulated in HCC tissues and it is known to regulate E2F3 and ZEB2 genes, which are up-regulated in HCC cancer." (PMID 35629174, 2022). "Our work demonstrates that E2F3-induced MEX3A directly suppresses terminal differentiation regulator KLF4 to activate WNT signaling, that in turn sustains cancer cells in rapidly-dividing and undifferentiated state." (PMID 36276637, 2022). "Among the universal DEGs, 4 upregulated genes (BGN, E2F3, PLAU, and SPP1) and 1 downregulated gene (UBL3) were found to be cancer genes already documented in the COSMIC or F-Census databases." (PMID 33542925, 2021). "In all analyzed cancer cells, IGF2BP1 depletion significantly reduced E2F1–3 mRNA levels, with the exception of A549 cells where E2F3 transcripts were modestly elevated." (PMID 32761127, 2020). "Few transcription factors, such as E2F1 and E2F3, have been shown to activate RRM2 gene transcription in cancer cells." (PMID 31936661, 2020). "Inactivation of RB1 expression in cancer leads to the deregulated activity of the transcription of E2F1, E2F2, and E2F3." (PMID 32429447, 2020).